MYC (MYC proto-oncogene, bHLH transcription factor)
Diseases named in the same sentence as MYC in open-access papers (continued):
Sharing a sentence is not in itself a finding about the gene and the disease.
tumor (continued). "Other key molecules including MYC, and KRAS in amino acid metabolic signaling pathway are also burgeoning approaches for tumor biotherapy." (PMID 38218942, 2024). "According to the fifth edition of the WHO Classification of Tumours of Haematopoietic and Lymphoid Tissues, 26 patients (93%) were classified as DLBCL-NOS, and 2 patients (7%) were classified as HGBCL with MYC and BCL2 rearrangements." (PMID 38542066, 2024). "231DD shows enhanced expression of ES-TFs SOX2, MYC, and NANOG and tumor sphere formation compared to vector control 231 cells." (PMID 38886396, 2024). "repressing IGF2BP3/c‐MYC/LOC101929709/LIN28B/PI3K–AKT pathway inhibited the Warburg effect and tumor progression." (PMID 38721006, 2024). "We then analyzed NOX4 protein levels in multiple tumor cells and primary tumor samples, and found NOX4 expression was markedly elevated in MYC(N)-high tumor cells and tumor samples." (PMID 38493213, 2024). "On the other hand, TEAD can play an important role in tumor progression, metastasis, tumor metabolism, immunity and drug resistance through transcription and regulation of KRAS, BRAF, LKB1, NF2 and MYC." (PMID 38553612, 2024). "The hypoxic state of the tumor microenvironment induces mitochondrial defects and promotes Tex in the TIME via the MYC regulatory pathway." (PMID 38280005, 2024). "The tumors were defined by nine tumor states, each characterized by the differential activity of nine key pathways: NRF2-PPP, NFkB-SRC-JUN, TCA Cycle, DNA Repair-MYC-E2F, PI3K-EMT-Stem, WNT-BCAT-AKT, NFkB-IRF-KLF5, EGFR-p63, and EMT-ZEB1." (PMID 38505587, 2024). "Consistent with our in vitro findings, immunohistochemistry (IHC) staining and western blotting of tumor xenografts five days post treatment confirmed significant downregulation of p300/CBP, AR, PSA, MYC, Ki67, CCND1, NKX3–1, CITED2, H3K27ac, and H2BK20ac." (PMID 38586029, 2024). "Together, our results suggest a profound antitumor effect of JHU083 via impaired tumor cell metabolism, leading to disruption of HIF-1α and c-MYC signaling." (PMID 38701369, 2024). "The regulation of integrin proteins by MYC and PHGDH provides a valuable insight into how oncogenes can modulate tumor cell plasticity." (PMID 39883338, 2024). "CMS2 or the canonical subtype (40% of early-stage tumours) are epithelial tumours with the activation of WNT and MYC as well as EGFR signalling and a high expression of cyclins." (PMID 38339195, 2024). "This was in sharp contrast with control mice transfected with MYC and RFP (i.e., control empty vector) for which only 2 mice out of 10 presented tumors (1 tumor per liver), despite the extended delay of their sacrifice, up to 14 weeks post-HGT." (PMID 38228803, 2024). "Regulated by MYC, ADHFE1 enhances tumor growth and promotes a stem cell-like phenotype, thereby increasing tumor aggressiveness." (PMID 39408832, 2024). "NANOG also works together with other stemness factors, such as KLF4, MYC, OCT4, or SOX2, to control target genes that have important functions in embryonic stem cells and, plausibly, in tumor cells." (PMID 37165076, 2023). "The “Use with Caution” antibodies in this set include antibodies that bind the protein products of frequently altered cancer driver genes, such as the oncogenes MYC and BRAF and the tumour suppressors BRCA2 and VHL." (PMID 37169592, 2023). "Another interesting target of FBXO45, FBXW7, is a tumour suppressor that targets specific substrates for ubiquitination and degradation, including the known driver oncogenes of aggressive PCA MYC and Mcl-1." (PMID 36980776, 2023). "Our results showed that MYC and TAF10 were significantly more highly expressed in cancer tissues than in adjacent non‐tumour tissues." (PMID 36639831, 2023).
tumor (continued). "Under severe hypoxia (<1% O2), NF-kB is activated by HIF-1α to enhance the invasive nature of tumor cells at the rim of GBM, whereas c-MYC is upregulated by HIF-2α under moderate hypoxia (2.5–5% O2) to promote the proliferation of tumor cells in GBM." (PMID 37835592, 2023). "MYCi975 is a small molecule inhibitor, which binds MYC directly to disrupt MYC-MAX interaction and increases the proteasomal degradation of MYC, and thus leads to decreased tumor growth." (PMID 37941901, 2023). "Ectopic expression of host oncogenes, MYC and PIK3CAE545K, enhanced clonogenic growth of both early- and late-passage HCK1T/16epi cells, but conferred tumor-initiating ability only to late-passage HCK1T/16epi cells." (PMID 36763589, 2023). "A similar combination was later tested with another BETi, CPI203, which achieved simultaneous downregulation of MYC and Bcl-2-related protein A1 (BFL-1), overcoming the emergence of resistance to venetoclax both in DHL cultures and tumor xenografts." (PMID 37457123, 2023). "In an established HCC patient-derived xenograft (PDX) model with positive expression of MYC and SCARB2, we observed that PMB suppressed the tumor growth and the combination of PMB and sorafenib further decreased the growth and weights of PDXs in mice." (PMID 37739936, 2023). "COMMD3 activates oncogenes such as c-MYC, which promotes prostate cancer cell proliferation, migration, and invasion; COMMD3 expression is positively connected with tumor recurrence and decreased survival rate." (PMID 36776284, 2023). "A further paracrine loop between CAF-derived FGF1 and cancer cell MYC activation has also been identified, with FGFR inhibition showing reduced MYC levels and tumour size, particularly when combined with MEK inhibition." (PMID 36357571, 2023). "CD133(+) TICs have an elevated level of MYC IRES activity, indicating that MSI2High cells supported increased levels of MYC protein synthesis through IRES-initiated, cap-independent translation to meet an adverse tumor microenvironment." (PMID 37117191, 2023). "Consistent with the findings, a study found that loss of METTL3 dramatically repressed cancer cell proliferation, invasion, and xenograft tumor formation via AFF4, NF-κB, and MYC signaling networks." (PMID 39872957, 2023). "For instance, in c-MYC-induced HCC tumors, TAZ depletion results in tumor regression, corroborating a facilitating role of YAP activation in c-MYC-induced hepatocarcinogenesis." (PMID 37627221, 2023). "GSEA of premalignant livers from LP245/+ compared with LP+/+ revealed that tumor-promoting pathways such as KRAS signaling, MYC, and epithelial–mesenchymal transition (EMT) pathways were enriched in LP245/+." (PMID 38047594, 2023). "Within a tumor core, where cells showed a range of RUNX3 and MYC expression levels, the inverse correlation of RUNX3 and MYC expression was clearly evident." (PMID 37400551, 2023). "Moreover, several studies have indicated that the transcription factor MYC served as a proto-oncogene in multiple cancers, which can result in transcriptional activation or repression of specific genes including those involved in tumor cell growth, proliferation, and survival." (PMID 37908977, 2023). "In comparing gene expression profiles of our MYC/SMARCA4 tumors to an established SHH MB model, we identified upregulation of G protein signaling and glucose metabolism in our tumor model." (PMID 37919824, 2023). "Frequently upregulated MAPK pathway genes in resistant tumours were apart from DUSP6 different FGFs, MYC, EPHA2, and FOS." (PMID 37604687, 2023). "Further, it was observed that IGHG1 inhibition controlled the tumor growth and inactivation of the MEK/ERK/c-MYC pathway." (PMID 37895357, 2023). "MYC can cooperate with RAS to transform rodent cells, and we previously reported that the expression of MYC significantly enhances a tumor initiating property of HCKs expressing HPV16 E6E7 driven from heterologous promoters and HRASG12V." (PMID 36763589, 2023).
tumor (continued). "Another illustrative example is furnished by the interaction between RUNX3 and the proto-oncogene MYC, and the consecutive binding to the promoter of TGF-β1, leading to CAF activation and tumor progression in colorectal cancer." (PMID 38124183, 2023). "By analyzing different tumor-infiltrating CD8+ T cell subpopulations, we found reduced expression of both MYC and SLC7A5 in memory-like CD8+ TILs, which is in line with our in vitro findings." (PMID 36717749, 2023). "Overexpression of the upstream regulator MYC has previously been shown to reversibly induce and maintain CIN, contributing to aneuploidy, tumorigenesis, and tumour evolution." (PMID 37622176, 2023). "Two key groups of MYC synthetic lethal targets are regulators of MYC transcription (e.g., BRD4 and CDK9) and MYC stability (e.g., aurora kinases A and B, and polo‐like kinase 1), regulating the levels of MYC in tumor cells." (PMID 36684069, 2023). "As a result of interactions between BMH-21 and BA-41 and the DNA G-quadruplex structure, as well as the c-MYC G-quadruplex, the expression of c-MYC is downregulated in human tumor cells." (PMID 38002277, 2023). "Comparing ESCC tissues to non-tumor tissues, we found significant upregulation of PVT1, CCAT1, and c-MYC." (PMID 36624401, 2023). "MSI2 binds the internal ribosome entry site (IRES)-containing oncogene mRNAs including MYC, JUN and VEGFA as well as HCV IRES to increase their synthesis and promote self-renewal and tumor-initiation at the post-transcriptional level." (PMID 37117191, 2023). "The relationship between KRAS and MYC in tumorigenesis is very complex but BET inhibition in mouse models of KRAS-driven PDAC and NSCLC reduced both tumor size and tumor grade." (PMID 38023987, 2023). "Both FZD7 and c-MYC are considered to be potential markers of tumor cells; therefore, we speculated that the link between proliferation and apoptosis in the immature Sertoli cells was similar to that in tumor cells, and that this mechanism was influenced by the expression level of FZD7." (PMID 37047150, 2023). "Still, MYC was able to rescue these MYCN-suppressed cells and became the key driver of proliferation, leading to complete rescue and survival of tumor cells." (PMID 36869047, 2023). "In fact, the stem cell factors Nanog and SRY-box 2 facilitate MYC-mediated induction of HIF2A, playing a critical role in stem cell renewal and tumor stemness." (PMID 37998757, 2023). "Remarkably, the combination of sgRUVBL1 and JQ1 dramatically inhibited the in vivo EwS tumor progression (red), providing a proof‐of‐concept efficacy of synergistic targeting RUVBL1 and MYC in EwS." (PMID 37075745, 2023). "Results showed that the high value of regulatory potential between MFAP5 and some of its top predicted NOTCH1/WNT pathway target genes (CCND1, HES1, MYC, RBPJ, NOTCH1, CCN3, CTNNB1 and SOX17) in inferring signaling paths in tumour tissues." (PMID 36855786, 2023). "Among the exclusively detectable Exo-prots in the NB patients, we identified the MYC target nucleophosmin (NPM1) and the actin interacting protein zyxin (ZYX), known for their role in tumor proliferation and invasiveness." (PMID 37947594, 2023). "Besides directly suppressing tumor growth via the inhibition of Brd4 and c-MYC transcription, NHWD-870 also suppressed the proliferation of tumor-associated macrophages (TAMs) through reducing the expression and secretion of the macrophage colony stimulating factor CSF1 by tumor cells." (PMID 37049806, 2023). "For the differentiation between tumor and non-tumor tissue the ROC analysis revealed an AUC of 0.73 (95% CI 0.66, 0.80) for TERT and 0.72 (95% CI 0.65, 0.79) for MYC." (PMID 37858127, 2023). "Recently, we have shown that the determination of v-myc avian myelocytomatosis viral oncogene homolog (MYC) CNV is an appropriate tool to discriminate between lung tumor and non-tumor tissues with a sensitivity of 43% and 99% specificity." (PMID 37858127, 2023).
tumor (continued). "In a study by Pectasides and colleagues, genomic tissue profiling identified discordance of common alterations (HER2, MYC, CCND1, EGFR) between primary tumor and metastasis in 32% of patients." (PMID 35834132, 2023). "The small protein ME47 disrupts the MAX:E-box interaction, leading to a block of MYC/MAX transcription and inhibition of tumor growth." (PMID 36969025, 2023). "Reduced APC expression unleashes the suppression of MYC and PKM2, thereby leading to enhanced aerobic glycolysis, tumor cell proliferation and tumor formation." (PMID 37192910, 2023). "IFN-γ also notably upregulates the otherwise minimal expression of PD-L1 of MYC-amplified MBL in vivo, thereby abrogating T cell-mediated anti-tumour function and eventual apoptosis." (PMID 37232837, 2023). "We, thereby, performed the Kaplan–Meier and log-rank test analyses using the MYC and CCNE1 amplifications that were assessed by either tumor tissue or CSF samples." (PMID 37131253, 2023). "The researchers showed through luciferase-binding experiments that MYC binds to the SLC1A5 promoter to initiate SLC1A5 transcription and promote glutamine uptake, to finally achieve tumour metastasis." (PMID 37829798, 2023). "Next, we analyzed the effects of PME‐1 silencing on the phosphorylation of pro‐survival kinase AKT and oncoprotein MYC by western blotting and by immunohistochemistry analysis of CAM tumours." (PMID 36461911, 2023). "There were positive correlations among USP13, MYC, and SOX2 at the protein level in human LUSC Clinical Proteomic Tumor Analysis Consortium (CPTAC) proteomic data." (PMID 38093367, 2023). "Hypoxia promotes a stem-like phenotype in tumor cells through the activation of genes such as OCT4, SOX2, c-MYC, CD44, CD133, WNT, Notch, and NANOG, leading to dedifferentiated and undifferentiated tumor phenotypes associated with more aggressive biology." (PMID 38132455, 2023). "A CRISPR interference (CRISPRi) screen of non-coding regions near the MYC locus found the promoter of nearby PVT1, which is subject to structural rearrangements in cancer, to be a non-coding tumor suppressor element." (PMID 37415185, 2023). "Translocations involving MYC, most often as IGH::MYC fusion, have been detected in 50% of cases, and EBV infection of the tumor cells is found in 70% of cases." (PMID 37190213, 2023). "Univariate analysis indicated the patients with stages III-IV, B symptoms, tumour recurrence, PAX5 positivity, and c-MYC positivity showed a shorter survival time (p<0.05)." (PMID 36634942, 2023). "TF factor motif analysis within H3K27ac peaks revealed 29 MG63-specific TF binding sites, including those for EOMES, PRDM1, EPAS1 (HIF2A), E2F6, and MYC/MAX, which reflect known early development, tumor-initiation, and stemness factors (Worksheet 1)." (PMID 37228489, 2023). "The tumor-proliferation subtype showed rare TIL infiltration and significant activation of E2F targets, MYC targets, and DNA repair and mTORC1 pathways, suggesting tumor cell proliferation." (PMID 37488287, 2023). "Elevated m6A levels on MYC mRNA promote the binding of YTHDF1, thereby promoting its translation and increasing glycolysis, tumor cell proliferation, and tumorigenesis." (PMID 37007161, 2023). "Briefly, overactivation of MYC in innate immune cell subsets may be detrimental to the production of proinflammatory mediators, such as interferon, may increase immunosuppressive cytokine production, and may restrain the tumor-killing activities of effector cells, such as NK cells." (PMID 36966168, 2023).
tumor (continued). "Accumulated evidences have suggested that MYC was an important oncogenic factor in RMS, and its upregulation is closely related to tumor aggression and poor clinical outcome." (PMID 36793601, 2023). "Furthermore, a significant enrichment of pathways associated with poor tumor prognosis was observed in the high-risk group through the GSEA analysis, such as “E2F targets pathway”, “G2M checkpoint pathway”, “MTORC1 signaling pathway”, “MYC targets pathway”, and “RIBOSOME”." (PMID 37629096, 2023). "For c-MYC, it has already been shown in PDAC and other tumor entities that inhibition of BET proteins reduces the transcription of c-MYC and causes growth inhibition." (PMID 37719017, 2023). "PLK1 and MYC create a positive feedforward activation loop that sustains a high expression, and PLK1 inhibitors induce apoptosis in MYC-overexpressing tumor cells, highlighting their potential as therapeutics for MYC-dependent cancers." (PMID 37755397, 2023). "Some key molecular switches, such as Src and Ras, which regulate important protein families such as MYC and FAK, enhance tumor cells' anti-apoptotic capacity to combat tumor suppression response and cancer therapy in the organism." (PMID 36707854, 2023). "Preclinically, this broad-spectrum HDACi decreased the expression of both MYC and BCL2 and was able to elicit a significant reduction in tumor growth." (PMID 37457123, 2023). "In vivo, a xenograft assay demonstrated that MYC knockdown markedly enhanced the inhibitory effects of HMA on tumor growth, with decreased tumor mass, tumor volume, and ratio of the Ki-67-positive cells." (PMID 36717782, 2023). "An upstream regulatory factor MYC and STAT3 are constitutively activated in many cancers and plays a pivotal role in tumor growth and metastasis by regulating cell proliferation, invasion, migration, and angiogenesis." (PMID 36845724, 2023). "The frequency of CCNE1 amplification, MYC amplification, CDKN2A deletion, and PTEN deletion was higher in CSF than in primary tumor tissues." (PMID 37131253, 2023). "β-catenin promotes tumour development by regulating the expression of immune escape-related molecules (CCL4, CD47 and PD-L1) through transcription factors (MYC, TCF/LEF, NF-κβ, SNAI1, etc.)." (PMID 36646807, 2023). "This XIST-driven production of IL-6 from ALDH− bulk tumor cells preferentially binds to IL6R on ALDH+ CSCs to drive STAT3 activation and expression of key CSC factors (i.e., c-MYC, KLF4 and SOX9), promoting self-renewal of ALDH+ CSCs." (PMID 36922677, 2023). "Inactivation of the TRE promoter and hence prevention of activation of MYC in embryonic GMYC mice led to prevention of tumor formation and a complete tumor-free life span in the majority (84%) of cases." (PMID 36869047, 2023). "MYC affects related immune activities by regulating innate and adaptive immunity in the TIME to promote tumor proliferation." (PMID 36966168, 2023). "The splicing of HRAS exon 5 was found to be particularly responsive to MYC activity, and the correlation between HRAS splicing and MYC activation is found in other tumor types." (PMID 37399401, 2023). "Except for inhibiting VEGF expression, c-MYC also decreased TSP-1 expression, facilitating tumor neovascularization." (PMID 36721232, 2023). "Dysregulation of immune signaling molecules induced by multiple signaling pathways regulated by MYC, including CTLA-4, CD47, and PD-L1, can help tumor cells directly or indirectly escape the immune response." (PMID 36966168, 2023). "A co‐expression analysis of tumor/adjacent tissue data from the CRC group revealed a correlation between the dysregulated miRNAs and CRC‐related genes (PVT1 and MYC) annotated in 8q24 region." (PMID 36366788, 2023).